TNF (tumor necrosis factor)
Diseases named in the same sentence as TNF in open-access papers (continued):
Sharing a sentence is not in itself a finding about the gene and the disease.
rheumatoid arthritis (continued). "Previous research had demonstrated secretion of inflammatory factors from chondrocytes by layilin signaling in rheumatoid arthritis (RA), they also found that TNF-α upregulated expression levels of layilin in the chondrocytes." (PMID 35770160, 2022). "Moreover, similarly to psoriasis, a positive correlation was observed in rheumatoid arthritis [RA] between the levels of IL-23 in serum and synovial fluid of patients and the production of other proinflammatory cytokines, i.e., IL-17, IL-1β or TNF-α." (PMID 33498653, 2021). "TNF-α is a cytokine that regulates a number of pro-inflammatory neutrophil functions, including granule mobilization, respiratory burst activity, and cytokine synthesis, and also plays a key role in chronic inflammatory diseases such as rheumatoid arthritis and gout." (PMID 34234773, 2021). "TNF-α has been identified as a pivotal cytokine in the pathogenesis of both atherosclerosis and autoimmune diseases such as rheumatoid arthritis (RA) and psoriasis." (PMID 34803716, 2021). "GSEA analysis indicated that OSA is predominantly associated with an IL-17 signaling pathway, pertussis, rheumatoid arthritis, parathyroid hormone synthesis, secretion, and action, TNF signaling pathway, amyotrophic lateral sclerosis, and non-alcoholic fatty liver disease." (PMID 34880901, 2021). "Tumor necrosis factor inhibitor (TNFi) therapies are often the first biologic therapy used to treat rheumatoid arthritis (RA) patients." (PMID 33258003, 2021). "Survival rate of patients receiving anti-TNFα treatment appears to be greater in PsA vs. rheumatoid arthritis (RA) patients." (PMID 34136971, 2021). "Moreover, anti-TNFα treatment infliximab causes an increase in circulating non-classical monocytes in Crohn's disease patients, along with an increase in all CD16+ monocytes in rheumatoid arthritis patients." (PMID 35155614, 2021). "This study assesses the IR and beta cell function in rheumatoid arthritis (RA) patients with active disease compared to osteoarthritis (OA) patients and investigates the effect of anti-TNF treatment on IR, beta cell function and body composition in RA." (PMID 32776224, 2021). "Inhibition of TNF-α signaling is a successful treatment strategy for many inflammatory and autoimmune diseases, such as rheumatoid arthritis (RA), ankylosing spondylitis, and inflammatory bowel diseases." (PMID 33770265, 2021). "In prior studies, TNF-α rs1800610 GA and AA genotypes were associated with a reduced risk in hepatocellular carcinoma, and AA genotype was observed to protect against rheumatoid arthritis, so we supposed that TNF-α rs1800610 AA might be a protective genotype in some pathogeneses." (PMID 34564376, 2021). "The Spanish registry of adverse reactions to biological therapies (BIOBADASER) has found a higher incidence of infections in patients with rheumatoid arthritis (RA) who receive anti-TNF therapies." (PMID 34149711, 2021). "Thus, the aim of this study was to evaluate the usefulness of the quantitative serum assessment of individual markers of bone turnover as indicators of the clinical efficacy of anti-TNF-α therapy with etanercept and adalimumab in women with rheumatoid arthritis." (PMID 34209821, 2021). "Finally, metabolic changes associated with two major treatment approaches were evaluated in patients suffering from rheumatoid arthritis, namely anti-tumor necrosis factor (TNF) inhibitors, including etanercept alone, or in combination with infliximab and methotrexate." (PMID 34681239, 2021). "In 1990, some investigators showed that TNF-α antagonists prevent adhesion molecule upregulation on the vascular endothelial cells in rheumatoid arthritis (RA) and experimental allergic encephalomyelitis." (PMID 34795583, 2021). "TNFα is also involved in rheumatoid arthritis (RA), a complex autoimmune disease, with a relatively constant prevalence of 0,5–1% in the world’s populations that affect many organs, including kidney, eyes, spleen, heart, and lungs." (PMID 33667229, 2021).
rheumatoid arthritis (continued). "Indeed, anti-TNF-α treatments alongside other inhibitory antibodies have transformed the pharmacological approach to chronic inflammatory diseases such as rheumatoid arthritis, psoriasis, and inflammatory bowel diseases, all being conditions with increased cardiovascular and cerebrovascular risk." (PMID 33770265, 2021). "In patients with rheumatoid arthritis (RA), inflammatory biomarkers, such as TNF-α or C-Reactive Protein, were inversely correlated to VB6 level in sera, but again VB6 medication in non-deficient subjects showed no beneficial effect." (PMID 34205653, 2021). "However, excessive production of TNF-α and IL-6 may lead to serious inflammatory disorders, including septic shock, rheumatoid arthritis, atherosclerosis, and cardiovascular diseases." (PMID 34071911, 2021). "Hence, QLY’s inhibition of IL-1β, IL-6, TNF-α, IL-2 and IFN-γ levels on AA rat serum might be part of the underlying mechanisms for QLY’s anti-rheumatoid arthritis effects." (PMID 34693865, 2021). "We previously reported that synovial mast cells (MCs) from patients with rheumatoid arthritis (RA) produced TNF-α in response to immune complexes via FcγRI and FcγRIIA." (PMID 33707464, 2021). "Etanercept is a fusion protein that inhibits TNF and has been successfully used to treat a variety of inflammatory disorders, namely severe rheumatoid arthritis (RA)." (PMID 34648530, 2021). "Tumor necrosis factor inhibitors (TNFi) are widely used for the treatment of patients with rheumatoid arthritis (RA), however a considerable percentage of patients discontinued the therapy." (PMID 34268325, 2021). "It was shown to be effective for the treatment of moderate to severe rheumatoid arthritis (RA) patients with an inadequate response to conventional synthetics disease modifying anti-rheumatic drugs (csDMARDs), including methotrexate or a TNF-α therapy." (PMID 33707483, 2021). "Anti-TNF-α biologics are used in rheumatoid arthritis (RA) with varying success, but for other autoimmune diseases such as multiple sclerosis, anti-TNF-α therapy has been shown to exacerbate disease." (PMID 33927722, 2021). "Conversely, patients with pro-inflammatory diseases such as rheumatoid arthritis experience a high burden of depressive symptoms, that improves following suppression of peripheral inflammation with cytokine blockers such as the anti-Tumor Necrosis Factor (anti-TNF) therapies." (PMID 32457424, 2021). "Glucocorticoids decrease IL-1β and TNF-α levels, improving the function of endothelium in rheumatoid arthritis (RA)." (PMID 33868242, 2021). "Therefore, this investigation aimed to evaluate the ocular surface parameters of rheumatoid arthritis patients and the impact of long-term TNF-inhibitors therapy on the ocular surface feature of rheumatoid arthritis patients, especially the evaluation of conjunctival goblet cell as a biomarker." (PMID 32820183, 2020). "Tumor necrosis factor-alpha (TNF-α) inhibitors have revolutionized the treatment of rheumatic diseases including rheumatoid arthritis (RA), ankylosing spondylitis (AS), and psoriatic arthritis (PsA)." (PMID 32867745, 2020). "It has been reported that GFD could substantially inhibit the activities of interleukin-6 and tumor necrosis factor-α in the serum of adjuvant-induced arthritis rats, as well as inhibit the formation of synovitis and pannus, and has obvious therapeutic effect on rheumatoid arthritis." (PMID 32754034, 2020). "Furthermore, tumor necrosis factor alpha (TNF-α) is a pro-inflammatory cytokine and its dysregulation has been linked to the onset of various human diseases, including cardiovascular diseases, rheumatoid arthritis, Alzheimer’s disease, and psoriasis." (PMID 32230808, 2020). "Variation of STXBP6 might affect the response of TNF-α inhibitors in rheumatoid arthritis patients." (PMID 32296631, 2020). "The objectives are to describe the profile of rheumatoid arthritis (RA) patients treated with anti-TNF agents in Canadian routine care." (PMID 32968710, 2020).
rheumatoid arthritis (continued). "For instance, abatacept (CTLA-4-Ig) is effective in alleviating disease activity in rheumatoid arthritis (RA) patients who have an inadequate response to methotrexate or anti-tumor necrosis factor (TNF)-α therapies." (PMID 32228715, 2020). "Indeed, when an anti-TNFα is administrated in patients with active rheumatoid arthritis, it has been demonstrated to induce a rapid decrease of a broad spectrum of cytokines (e.g. IL-6 and IL-1), as well as of others acute-phase related proteins and vascular permeability factor." (PMID 32467561, 2020). "The pathophysiology of rheumatoid arthritis (RA) is characterized by excess production of pro-inflammatory cytokines, including tumor necrosis factor-α (TNF-α), interleukin-1β (IL-1β), and interleukin-6 (IL-6) by neutrophils and macrophages in synovium." (PMID 32131874, 2020). "Galuteolin exerts protective effects against TNF-α-induced RA-FLS cells by inhibiting apoptosis and inflammation, which can guide the clinical use of rheumatoid arthritis." (PMID 33087158, 2020). "The tumor necrosis factor (TNF) superfamily cytokine TNF-like protein 1A (TL1A) and its receptor DR3 are essential for diverse animal models of autoimmune disease and may be pathogenic in rheumatoid arthritis (RA)." (PMID 32381123, 2020). "Tumor necrosis factor-α inhibitors (TNFis) have revolutionized the management of rheumatoid arthritis (RA), however despite considerable progress, only a small proportion of patients maintain long-term clinical response." (PMID 32318070, 2020). "This study was performed to evaluate the effects of 15-month anti-tumor necrosis factor α (anti-TNF-α) therapy on the aggrecan turnover of female rheumatoid arthritis (RA) patients." (PMID 32392807, 2020). "One study found that immune-mediated inflammatory disease patients receiving anti-TNF-α treatment had elevated rates of mycobacterial disease and that NTM disease was associated with rheumatoid arthritis (RA)." (PMID 32781595, 2020). "TNF-α antagonists were initially used in the treatment of rheumatoid arthritis (RA) at the end of the 1990s." (PMID 32151118, 2020). "Therapies that block tumor necrosis factor (TNF) have dramatically improved patient outcomes in several autoimmune diseases, particularly rheumatoid arthritis (RA)." (PMID 32381123, 2020). "For these reasons, anti-TNF-α antibodies are used to treat some autoimmune diseases, such as rheumatoid arthritis (RA)." (PMID 32063984, 2020). "The inflammatory diseases rheumatoid arthritis (RA) and periodontitis show similarities in misbalances of cytokine levels, such as tumor necrosis factor-α (TNF-α)." (PMID 33193432, 2020). "Targeting macrophages using nanoparticles to silence TNF-α is widely reported to reduce inflammation in rheumatoid arthritis (RA), intestinal inflammation/injury and LPS-induced inflammation." (PMID 33348630, 2020). "In addition, two reports have described that anti-TNFα therapies cause an increased risk of non-melanoma skin cancers and hematological malignancies in patients with rheumatoid arthritis." (PMID 32391269, 2020). "Liu et al18 reported that in rheumatoid arthritis (RA), inflammatory cytokines, including tumor necrosis factor‐α (TNF‐α) and IFN‐γ, promoted the expression of soluble PD‐1 in the plasma." (PMID 32065479, 2020). "Likewise, two previous systematic reviews reported that null findings of replicated effects of MBIs were observed for inflammatory cytokines in blood, including IL-6 and TNF-α, in participants with cancer, ulcerative colitis or rheumatoid arthritis, or in dementia caregivers and healthy controls." (PMID 32260096, 2020). "It is well known that T cells and increased levels of cytokines, such as TNF-α are involved in the development of these conditions that include, among the others, rheumatoid arthritis (RA), autoimmune hepatitis (AIH), or sepsis." (PMID 31899535, 2020).
rheumatoid arthritis (continued). "Approved indications for TNF blockers include rheumatoid arthritis (RA), ankylosing spondylitis, psoriasis, psoriatic arthritis, ulcerative colitis (UC) and Crohn’s disease (CD) which are subtypes of inflammatory bowel disease (IBD)." (PMID 32203525, 2020). "TNFα plays an important role in the pathogenesis of many chronic inflammatory diseases and its inhibition has been shown to be an effective approach for therapy of rheumatoid arthritis, psoriatic arthritis, ankylosing spondylitis, psoriasis and inflammatory bowel disease." (PMID 32093030, 2020). "Moreover, in a small multicentre, open‐label, randomized clinical trial that compared anakinra with a host of TNF‐α blockers, IL‐1 inhibition with anakinra also proved effective in improving glycemic and inflammatory parameters in patients affected with rheumatoid arthritis and type 2 diabetes." (PMID 32770571, 2020). "Previously, it was shown that anti-TNF therapy is able to reduce the expression of TLRs in monocytes from patients with rheumatoid arthritis (RA) and spondylarthopathy." (PMID 32164729, 2020). "However, sclerostin antibody treatment may promote TNF-dependent inflammatory joint destruction in rheumatoid arthritis patients." (PMID 32708317, 2020). "Furthermore, GrA may contribute to rheumatoid arthritis partly by promoting mice osteoclast precursor differentiation via the stimulation of TNF-α secretion of monocytes and osteoclast precursors present in the inflammatory joint." (PMID 32508827, 2020). "Activates p38 and Akt pathways and increase expression of HDAC6 by more than 200% in rheumatoid arthritis synovial fibroblasts.Increases HDAC6 expression, which led to enhancement of the detrimental effects of TNF-α in RA synovial fibroblasts." (PMID 32397127, 2020). "Studies confirmed that TNF-α is a powerful proinflammatory cytokine overexpressed in the synovium of patients with RA, and reducing TNF-α production can effectively improve the symptoms of rheumatoid arthritis(Marsal and Juliá, 2010)." (PMID 33013406, 2020). "TNF-α inhibitors, such as Infliximab, Adalimumab, or Etanercept, have been investigated for the treatment of rheumatoid arthritis (RA) and inflammatory bowel disease, and are commercially available for more than 15 years." (PMID 32587853, 2020). "Hereby, we report a 71-year-old female with seronegative rheumatoid arthritis who presented with massive splenomegaly, pancytopenia, and positivization of antibodies against double-stranded deoxyribonucleic acid (dsDNA) after initiation of the anti-tumor necrosis factor (TNF) golimumab." (PMID 32328321, 2020). "Good examples of known shared risk loci in IMDs are PTPN22, IL23R and TNFAIP3, which have allowed the repositioning of anti-TNF and anti-IL-12/IL-23 therapies to be used in rheumatoid arthritis (RA) and systemic lupus erythematosus (SLE), among others." (PMID 33317201, 2020). "We sought to investigate whether genetic effects on response to TNF inhibitors (TNFi) in rheumatoid arthritis (RA) could be localised by considering known genetic susceptibility loci for relevant traits and to evaluate the usefulness of these genetic loci for stratifying drug response." (PMID 31036624, 2019). "TNFα role has been well-established in the etiology of rheumatoid arthritis (RA), inflammatory bowel disease (IBD), psoriasis, plaque psoriasis, Behçet’s disease, sarcoidosis, and ankylosing spondylitis." (PMID 31584996, 2019). "For example, rheumatoid arthritis (RA) synovial macrophages are the main TNFα producing cells in the inflamed synovium." (PMID 31216336, 2019). "Although, several other inflammatory cytokines are elevated in RA (rheumatoid arthritis), anti-TNF therapy seems to be promising for the effective treatment against it." (PMID 31031770, 2019).
rheumatoid arthritis (continued). "In light of the fact that inflammatory bone loss diseases may occur simultaneously, anti-TNF-α treatment could benefit more than one disease, as was shown for instance in rheumatoid arthritis patients receiving anti-TNF-α medication infliximab, who had lower periodontal indices." (PMID 30941138, 2019). "Rheumatoid arthritis (RA) and Crohn′s disease (CD) are two well-known examples of inflammatory diseases in which the prominent role of TNF-α has been proved." (PMID 31531059, 2019). "Antitumor necrosis factor α antibodies (anti-TNFα Abs) constitute a major advance in rheumatoid arthritis (RA) therapy in the clinic, as targeting TNFα in the disease region can reduce pathological inflammation and efficiently inhibit RA progression." (PMID 31194726, 2019). "However, TNF-α antagonists such as etanercept, infliximab, or adalimumab proved to be a highly effective treatment for auto-inflammatory diseases like psoriasis, Crohn’s disease, or rheumatoid arthritis." (PMID 31795299, 2019). "Although disease in a majority of rheumatoid arthritis (RA) patients is often initially limited to one or a few joints, currently approved medications including anti-tumor necrosis factor-α antibody (α-TNF) are injected systemically." (PMID 31870429, 2019). "TRPs are also involved and upregulated in rheumatoid arthritis (RA) where the preincubation of synovial fibroblasts with TNF upregulated and sensitized TRPA1, reducing cell viability by inducing necrosis." (PMID 31197115, 2019). "Macrophages are a major source of inflammatory cytokines (e.g., TNFα, IL6, and IL1) implicated in the pathogenesis of inflammatory diseases such as rheumatoid arthritis (RA) and inflammatory bowel disease (IBD)." (PMID 31552020, 2019). "We aimed to determine the effect of TNF-α inhibitors (TNFi) on peripheral blood monocyte subpopulations and their activation in ankylosing spondylitis (AS) and rheumatoid arthritis (RA) patients with high disease activity." (PMID 30642076, 2019). "In addition to hypoxia and oxidative stress conditions induced by the effect of PE, other KEGG pathways were dysregulated such as rheumatoid arthritis, T-cell and B-cell receptor signaling, chemokine, Jak-Stat, TNF, Toll-like-receptor, WNT and osteoclast differentiation signaling pathways." (PMID 31766745, 2019). "It has been reported that IL-33 was expressed in synovial fibroblasts from patients with rheumatoid arthritis (RA), and expression was markedly elevated in vitro by TNFα and IL-lβ stimulation." (PMID 30863362, 2019). "Pro-inflammatory cytokines, like IL-6, IL-8, IL-18 and TNF are involved in the inflammatory process of autoimmune diseases, such as rheumatoid arthritis (RA) and SLE." (PMID 31195707, 2019). "The clinical success of biologics that inhibit TNF (Tumor Necrosis Factor) in inflammatory bowel diseases (IBD), psoriasis and rheumatoid arthritis (RA) has clearly established a pathogenic role for this cytokine in these inflammatory disorders." (PMID 31457011, 2019). "Inhibitors of tumor necrosis factor alpha (TNF-α) are current mainstay of therapies for rheumatoid arthritis (RA)." (PMID 30886998, 2019). "We report a case of Orf disease affecting the hand of a patient with rheumatoid arthritis (RA) on treatment with methotrexate and adalimumab, an anti-tumor necrosis factor biological agent." (PMID 32185306, 2018). "Furthermore, another retrospective study in which anti-TNF agents were used in larger therapeutic doses for up to 10 years in a very small group of patients with rheumatoid arthritis and Crohn's disease resulted in significantly better glycemic control in patients with coexistent type 2 diabetes." (PMID 29576769, 2018). "Tapering of anti-tumour necrosis factor (TNF) therapy appears feasible, safe and effective in selected patients with rheumatoid arthritis (RA)." (PMID 29862047, 2018).